KRAS (KRas proto-oncogene, GTPase)
Diseases named in the same sentence as KRAS in open-access papers (continued):
Sharing a sentence is not in itself a finding about the gene and the disease.
small cell lung carcinoma (48 papers, 2010 to 2026). Small cell lung cancer (SCLC) is a highly aggressive malignant neoplasm, accounting for 10-15% of lung cancer cases, characterized byrapid growth, and early metastasis. "We now know that activation of MET or HER2 amplification, acquisition of mutations in BRAF, PIK3CA, and KRAS, histological transformation to small cell lung cancer (SCLC), and epithelial-to-mesenchymal transition (EMT) are major reasons." (PMID 39497713, 2024). "The EC50 values against the NCI-H23 cells were significantly lower than the EC50 values obtained against NCI-H1299, a non-small cell lung cancer cell line that lacks a KRAS mutation." (PMID 39436906, 2024). "Although KRAS mutations, especially G12C, are strongly associated with smoking, KRAS mutations are surprisingly unfrequent in small cell lung cancer, which occurs almost exclusively in heavy smokers." (PMID 38953007, 2024). "In small cell lung cancer, smokers aged >40 years with the KRAS let-7 (KRAS-LCS6) variant possessed an increased risk of disease." (PMID 24932237, 2014). "A dose-dependent inhibition of tumor growth was observed upon twice daily oral administration of BI-2493 in nude mice bearing tumors derived from the KRAS WT–amplified small cell lung cancer cell line DMS 53 (CN = 9.5)." (PMID 39711431, 2025). "These engineered exosomes were capable of selectively delivering KRAS siRNA to non-small cell lung cancer cells that expressed the αvβ3 integrin, effectively downregulating the KRAS gene, inhibiting tumor proliferation, and demonstrating negligible toxicity." (PMID 40264760, 2025). "The chimeric siRNA’s improved potency was also observed in small-cell lung cancer lines that are MYC-dependent with wild-type KRAS." (PMID 40762837, 2025). "NCI-H441is a KRAS-dependent lung adenocarcinoma cancer cell line, and NCI-H1975 is a non–small cell lung cancer cell line harboring EGFR L858R/T790M activating mutations." (PMID 37824212, 2023). "Non–small cell lung cancer cell lines with KRAS/STK11 comutations were more sensitive to a CHK1/2 inhibitor than cell lines without STK11 comutations." (PMID 36381660, 2022). "DEGs found to be associated with the small cell lung cancer pathway (ITGA2) and other cancer pathways (MMP1), based on KEGG analysis, were highly expressed in KRAS-mutant AAH." (PMID 34943992, 2021). "We therefore choose the KRAS mutant non–small-cell lung cancer (NSCLC) cell line (A549 cell line) as our experimental model system." (PMID 29522507, 2018). "There was a recent report that USP7 could deubiquitinate KRAS and maintain its expression in small cell lung cancer cells." (PMID 40473213, 2025). "The authors categorize resistance into EGFR-dependent mechanisms (e.g., secondary mutations like T790M and C797S), bypass pathway activation (e.g., MET or HER2 amplification, KRAS mutations, and BRAF mutations), and histologic transformation (e.g., small-cell lung cancer)." (PMID 40416863, 2025). "Approximately 5% of small-cell lung cancer (SCLC) and 39% of NSCLC tumours harbour KRAS mutations." (PMID 36980522, 2023). "In the case of T790M loss, several genetic alterations have been observed, including those related to transformation to small cell lung cancer, MET amplification, ERBB2 amplification/mutation, PIK3CA mutation, KRAS mutations, and oncogenic gene fusion involving RET, FGFR3, and BRAF." (PMID 34831415, 2021).
small cell lung carcinoma (continued). "Effects of mutant KRAS or EGFR expression on phenotype and neuroendocrine markers in small cell lung cancer cells." (PMID 34121659, 2021). "Using this model, we here show that complete keratin loss in KRAS mutated lung tumors does not affect tumor morphology, invasion or metastasis, indicating that loss of the keratin cytoskeleton is not driving the transition of lung tumors into small cell lung carcinoma or a sarcomatoid phenotype." (PMID 23536778, 2013). "Like our observations in MYC-dependent small-cell lung carcinoma lines, KRAS silencing had no impact, consistent with RAS inhibitor resistance." (PMID 40762837, 2025). "Alternative signaling pathways, such as MET amplification, may also be activated, as are other mechanisms such as HER2 amplification, PIK3CA, KRAS, BRAF, and small cell lung cancer transformation." (PMID 39231972, 2024).
triple-negative breast carcinoma (48 papers, 2010 to 2026). An invasive breast carcinoma which is negative for expression of estrogen receptor (ER), progesterone receptor (PR), and human epidermal growth factor receptor 2 (HER2). "A stark contrast is observed in triple-negative breast cancer, where a substantial 65% are found to harbor a KRAS mutation." (PMID 39217242, 2024). "al, who also report mutations and amplifications of KRAS and the KRAS pathway in 11% and 93%, respectively, of triple negative breast cancer patients in the TCGA data set." (PMID 32463822, 2020). "Previous work has shown that the MAPK pathway is activated in triple negative breast cancer with the KRAS-variant, and is associated with lower estrogen signaling." (PMID 24732316, 2014). "Another study found the KRAS variant to act as a genetic marker for increased risk of developing triple negative breast cancer in premenopausal women (OR 2.31, 95% CI 1.26-4.22)." (PMID 22436609, 2012). "Since most basal-like tumors express EGFR, it seemed of interest to investigate the mutational status of KRAS in such tumors to provide scientific evidence for the evaluation of anti-EGFR therapies in the management of triple-negative breast cancer." (PMID 20385028, 2010). "Moreover, we also found that ERK inhibition strongly enhanced the RA-induced expression of RAR-target genes in MDA-MB-231 cells, which are highly aggressive, triple negative breast cancer (TNBC) cells harboring an oncogenic KRAS mutation." (PMID 36497371, 2022). "In addition, we observed higher KRAS mutations among the patients with triple-negative breast cancer in our cohort than in the TCGA cohort." (PMID 33968723, 2021). "For one, KRAS variants regulate the development of triple-negative breast cancer." (PMID 33801965, 2021). "However, some KRAS mutations preferentially signal through the PI3K pathway, this may explain the partial response observed with BKM120 in a patient with triple negative breast cancer whose tumor harbored a KRAS mutation." (PMID 23232172, 2012). "It is of note that high MSLN expression was linked to several key molecular features in the cancer types analyzed, such as triple negative breast cancer and RAS (KRAS or NRAS) mutations." (PMID 33917081, 2021). "The partial reversal of the transdifferentiation program corresponds to our findings that luminal epithelial cells gave rise to claudin-low tumors in the oncogenic KRAS-driven, triple-negative breast cancer model." (PMID 34145248, 2021). "This is interesting because the SUM-229 line is a KRAS-transformed cell line that falls into the basal/claudin-low subset of triple-negative breast cancers and has been predicted by others to be enriched for expression of genes in the TGF-beta pathway." (PMID 32715085, 2020). "Breast malignancy with a high score enriched immune-related gene sets and pro-cancer-related gene sets, including epithelial–mesenchymal transition and KRAS pathway, in ER-positive/HER2-negative and triple-negative breast cancer (TNBC) groups." (PMID 35945417, 2022). "Currently, inhibitors have been produced that target downstream effector pathways of KRAS, including MEK inhibitors that are used to treat triple-negative breast cancer." (PMID 33801965, 2021).
cyst (45 papers, 2011 to 2025). A sac-like closed membranous structure that may be empty or contain fluid or amorphous material. "The same guidelines were revised in 2017, focusing on only IPMNs and including use of novel biomarkers, like CEA for cyst fluid analysis and genetic analysis for KRAS–GNAS mutations." (PMID 39766167, 2024). "Next-generation sequencing of cyst fluid for KRAS and GNAS mutations has shown high specificity for mucinous cysts." (PMID 39766167, 2024). "The presence of KRAS or GNAS mutations in the cyst fluid is reported to be highly specific for diagnosing mucinous PCLs." (PMID 36832238, 2023). "The established mouse xenograft tumors resulting from the inoculation of HOVs-cyst-1 cells with KRAS and PIK3CA mutations exhibited the micropapillary invasive pattern of LGSOCs with low nuclear atypia without alveoli." (PMID 35326657, 2022). "The Matrigel invasion assay also revealed that PIK3CA mutant HOVs-cyst-1 cells and HOVs-cyst-1 cells, with both KRAS and PIK3CA mutations, showed higher invasion abilities than the other cells." (PMID 35326657, 2022). "In this case, an undetermined morphological diagnosis was greatly enhanced by the data provided by Idylla (KRAS mutation) using the aspirated cyst fluid." (PMID 34063720, 2021). "One case (#64) with MCN with LGD harbored the 7% of KRAS mutant alleles in the surgically aspirated cyst fluid." (PMID 33082481, 2020). "The growth patterns were consistent in terms of cyst formation and solid growth from the 7th day onwards in both control and KRAS or BRAF mutated 3D cultures until the 10th day." (PMID 31545494, 2019). "Some studies showed cyst fluid analysis with KRAS mutation also seems to be a good diagnostic method to determine the malignant potential of pancreatic cystic lesions." (PMID 28969083, 2017). "In present cases, mutation analysis of molecular alterations showed a KRAS mutation in both the adenocarcinoma part and benign intestinal-type epithelium of the cyst." (PMID 25297496, 2014). "Genetic analysis of the cyst fluid also shows mutations, like KRAS and GNAS (less commonly in MCNs." (PMID 39766167, 2024). "EUS–fine-needle aspiration (EUS-FNA) allows cyst fluid analysis; however, CEA, glucose, and KRAS/GNAS mutations show poor value for malignancy risk." (PMID 41154400, 2025). "EUS-FNA enables the acquisition of cyst fluid for cytology, the presence of mucin, CEA, amylase, glucose, and KRAS/GNAS mutations." (PMID 41154400, 2025). "The aim of this study was to assess the additional role of KRAS and GNAS mutation analysis with Sanger Sequencing compared to conventional cyst fluid analysis with string sign, cytology, intracystic CEA, and glucose level measurement." (PMID 41464573, 2025). "Within this system, oncoproteins MUC1 and CD55, along with the oncogene KRAS, are identified in either cyst fluid or blood plasma specimens from a cohort of 39 patients." (PMID 38234100, 2024). "The molecular analysis of combined KRAS and GNAS mutations has a higher sensitivity, specificity, and diagnostic accuracy for diagnosing IPMNs and MCNs when compared to cyst fluid CEA alone." (PMID 36832238, 2023). "This study successfully developed an in vitro carcinogenic model of LGSOCs by introducing oncogenic KRAS and PIK3CA gene mutations in immortalized HOVs-cyst-1 cells from serous cystadenomas." (PMID 35326657, 2022). "Statistical analysis showed that the proliferative, migratory, and invasive abilities of HOVs-cyst-1 cells, with both KRAS and PIK3CA mutations, were significantly higher than the corresponding abilities of the HOVs-cyst-1 cells (p < 0.01)." (PMID 35326657, 2022). "Specifically, the presence of KRAS and GNAS mutations in cyst fluid has enhanced sensitivity and specificity for classifying mucinous lesions when compared with CEA and cytology." (PMID 35735595, 2022).
cyst (continued). "KRAS and GNAS mutations in the cyst fluid are particularly important early mutations in IPMNs as they are not found in other common types of cysts." (PMID 33673153, 2021). "This test utilises selected clinical features such as symptoms, cyst size and location, as well as cyst fluid genetic and biochemical markers, including cyst CEA levels and KRAS and GNAS mutation status." (PMID 33673153, 2021). "Existing diagnostic modalities (CT, MRI, EUS, CEA, and CA19-9 levels; KRAS and GNAS mutations; and cyst fluid cytology) are insufficient for accurately classifying IPMN patients due to their low diagnostic accuracy." (PMID 32842508, 2020). "Recently, mutations in KRAS and GNAS have been identified in the tissue and cyst fluid of patients with IPMN." (PMID 33005852, 2020). "Histologic and cyst fluid biomarkers for high-risk IPMN, including KRAS, GNAS, and MUC1/MUC2/MUC4/MUC5A, will be used in future decision making about treatment." (PMID 33145018, 2020). "In samples with unsatisfactory cytology (e.g. cyst content material, C1c), the analysis of KRAS from EUS-FNA material directly collected into a tube is the only way to evaluate the mutational status of the gene." (PMID 24504548, 2014). "Similarly, cyst fluid analysis in IPMN patients shows variable positivity rates, ranging from 26% to 82% for KRAS and 27% to 66% for GNAS mutations." (PMID 39219164, 2025). "This cyst showed non-mucinous characteristics on conventional testing; however, a KRAS mutation was detected." (PMID 41464573, 2025). "Furthermore, mutational analysis of driver genes, such as KRAS, GNAS, or KLF4, as well as miRNA sequencing and cyst fluid telomere fusion status seem to allow the discrimination of high-risk IPMN from low risk lesions." (PMID 36611137, 2023). "Conversely, the other cells (wild-type HOVs-cyst-1 cells or HOVs-cyst-1 cells, with either KRAS or PIK3CA mutation) did not induce tumor development in nude mice." (PMID 35326657, 2022). "Mutated KRAS and RNF43 detected from tumors, cyst fluid, pancreatic juice, and blood cell‐free DNA may serve as novel biomarkers of advanced neoplasia in the molecular surveillance and stratification for IPMN patients." (PMID 35229994, 2022). "Furthermore, oncogenic mutations, KRAS and PIK3CA, were individually and simultaneously introduced in immortalized HOV-cyst-1 cells." (PMID 35326657, 2022). "While in the absence of oncogenic KRAS solely RNF43 loss increased cyst size, its presence ascribed in both RNF43 and PTEN knockdown organoids a more cystic growth pattern compared to scramble controls." (PMID 31236113, 2019). "Molecular analysis of preoperative cyst fluid from the IPMN/MCN/PDAC group with 36 surgical specimens in total, showed at least one mutation in KRAS or GNAS genes in 31 (86.1%), including 16 of the 21 (76.2%) cases incorrectly classified by cytology (“NEG”: n = 9, “ND”: n = 7)." (PMID 31258847, 2019). "Conversely, in another meta-analysis the authors found that if cyst fluid mutational testing for KRAS/GNAS was negative, the probabilities that the patient has an IPMN or a mucinous cystic lesion would be approximately 2% and 8%, respectively, a finding with important practical consequences." (PMID 35892490, 2022). "Furthermore, analysis of the migration ability of the cells via an in vitro wound-healing assay showed that immortalized HOVs-cyst-1 cells, with both KRAS and PIK3CA mutations, had significantly (p < 0.01) higher migration abilities than HOVs-cyst-1 cells, with either KRAS or PIK3CA mutation." (PMID 35326657, 2022).
cyst (continued). "The feasibility of KRAS mutational status as a single marker has been evaluated in tissue, cyst fluid, duodenal fluid and plasma and does not appear to diagnose IPMNs or the level of cellular dysplasia consistently, being regarded as simply an early indicator of cell stress in pancreatic cells." (PMID 33673153, 2021). "we found that a KRAS mutation thought to be premalignant in mucinous clusters only, was also present in the other cyst lining epithelial cells of this unusual non-mucinous papillary variant of CPAM type 1, warranting clinical follow-up because of uncertain malignant potential." (PMID 32093717, 2020). "Two cyst fluid cases with molecular but not cytological evidence of a mucin-producing tumor (KRAS and/or GNAS mutations in the cyst fluid, no cells) were classified by SiMBiT as HG-dysplasia." (PMID 41142529, 2025). "A cohort of 39 samples, comprising 33 cyst fluids and 6 blood plasma specimens, underwent thorough examination utilizing both the SiMoT array – targeting oncoproteins MUC1 and CD55, and oncogene KRAS – and the SIMOA SP‐X planar technology, focused exclusively on MUC1 and CD55." (PMID 38234100, 2024). "HOVs-cyst-1 cells did not develop any colonies, whereas the double KRAS and PIK3CA mutant HOVs-cyst-1 cells, as well as HOVs-cyst-1 cells, with either KRAS or PIK3CA mutant, showed a small number of colonies compared with the SKOV3 cells." (PMID 35326657, 2022).